MRPL30 (mitochondrial ribosomal protein L30)
Synonyms: L28mt; MRP-L28; L30mt; MRP-L30; RPML28; uL30m; MRPL28M
Tractability: Small molecule: a structure with a bound ligand is known. PROTAC: ubiquitination databases record sites on it; its protein half-life has been measured.
Gene: Protein-coding gene on chromosome 2 (99,181,111 to 99,199,561, forward strand). Ensembl gene ENSG00000185414.
Subcellular location: Mitochondrion
Pathways (Reactome):
Metabolism of proteins: Mitochondrial ribosome-associated quality control; Mitochondrial translation elongation; Mitochondrial translation initiation; Mitochondrial translation termination
Gene Ontology:
Molecular function: structural constituent of ribosome
Biological process: mitochondrial translation; translation
Cellular component: mitochondrial large ribosomal subunit; mitochondrion; mitochondrial inner membrane; large ribosomal subunit
Genetic constraint (gnomAD): Loss-of-function variants: 11 observed, 16.59 expected, observed/expected ratio (o/e) 0.66, 90% interval 0.42 to 1.1. The upper end of that interval is the gene's LOEUF score, 1.1, which puts it in group 4 of 6, group 1 being the genes least tolerant of losing a copy. Missense variants: 163 observed, 176.67 expected, observed/expected ratio (o/e) 0.92, 90% interval 0.81 to 1.05. Synonymous variants: 57 observed, 55.5 expected, observed/expected ratio (o/e) 1.03, 90% interval 0.83 to 1.28.
Homologues: Orthologues: chimpanzee MRPL30 (99% identical), macaque MRPL30 (94% identical), pig MRPL30 (88% identical), dog MRPL30 (88% identical), rabbit MRPL30 (86% identical), rat Mrpl30 (85% identical), guinea pig MRPL30 (83% identical), mouse Mrpl30 (83% identical), rat LOC120100611 (66% identical).
Diseases named in the same sentence as MRPL30 in open-access papers:
MRPL30 is named in the same sentence as 4 diseases in open-access papers, as found by Europe PMC text mining. Sharing a sentence is not in itself a finding about the gene and the disease. The quoted sentences say what the papers report.
Obesity (2 papers, 2013 to 2021). Accumulation of substantial excess body fat. "Until now, there have been few studies on MRPL30, but one study reported that it could be a candidate gene for type 2 diabetes mellitus and obesity." (PMID 34116718, 2021). "The rest of the candidates, C2orf15, DENND1B, MRPL30, POC1B, RP4-655J12.3, TMBIM4, BMP2 K, CSRNP2, NCKAP5L, TOMM5, and BAP1, may be novel genes related to T2DM or obesity." (PMID 24455749, 2013).
colon cancer (1 paper, 2021). "Finally, the GTPase ERAL1, mitochondrial ribosomal proteins ERAL1, MRPL11, MRPL15, MRPL30, MRPL37, MRPL40, and MRPL52 were determined to be hub proteins with a commonly down-regulated trend in four berberine-treated colon cancer cell lines." (PMID 33806918, 2021).
MRPL30 also shares sentences with these, for which no sentence is quoted: tumor (1 paper); type 2 diabetes mellitus (1).